SPHK1 (sphingosine kinase 1)
Description:
Catalyzes the phosphorylation of sphingosine to form sphingosine 1-phosphate (SPP), a lipid mediator with both intra- and extracellular functions. Also acts on D-erythro-sphingosine and to a lesser extent sphinganine, but not other lipids, such as D,L-threo-dihydrosphingosine, N,N-dimethylsphingosine, diacylglycerol, ceramide, or phosphatidylinositol. In contrast to proapoptotic SPHK2, has a negative effect on intracellular ceramide levels, enhances cell growth and inhibits apoptosis. Involved in the regulation of inflammatory response and neuroinflammation. Via the product sphingosine 1-phosphate, stimulates TRAF2 E3 ubiquitin ligase activity, and promotes activation of NF-kappa-B in response to TNF signaling leading to IL17 secretion. In response to TNF and in parallel to NF-kappa-B activation, negatively regulates RANTES induction through p38 MAPK signaling pathway. Involved in endocytic membrane trafficking induced by sphingosine, recruited to dilate endosomes, also plays a role on later stages of endosomal maturation and membrane fusion independently of its kinase activity. In Purkinje cells, seems to be also involved in the regulation of autophagosome-lysosome fusion upon VEGFA. Has serine acetyltransferase activity on PTGS2/COX2 in an acetyl-CoA dependent manner. The acetyltransferase activity increases in presence of the kinase substrate, sphingosine. During neuroinflammation, through PTGS2 acetylation, promotes neuronal secretion of specialized preresolving mediators (SPMs), especially 15-R-lipoxin A4, which results in an increase of phagocytic microglia.
Synonyms: SPHK
Tractability: Small molecule: a structure with a bound ligand is known; a high-quality ligand is known; it belongs to a druggable protein family. Antibody: UniProt places it where antibodies can reach, with high confidence; its Gene Ontology location is reachable by antibodies, with high confidence; the Human Protein Atlas places it where antibodies can reach. PROTAC: a small molecule that binds it is known.
Target class: Enzyme
Chemical probes: CHEMBL2407198
Gene: Protein-coding gene on chromosome 17 (76,376,584 to 76,387,860, forward strand). Ensembl gene ENSG00000176170.
Subcellular location: Cytoplasm; Nucleus; Cell membrane; Endosome membrane; Membrane, clathrin-coated pit; Synapse
Subcellular location (Human Protein Atlas): Plasma membrane; Primary cilium; Primary cilium transition zone; Vesicles
Pathways (Reactome):
Signal Transduction: Extra-nuclear estrogen signaling; VEGFR2 mediated cell proliferation
Immune System: PKR-mediated signaling
Metabolism: Sphingolipid de novo biosynthesis
Metabolism of proteins: Association of TriC/CCT with target proteins during biosynthesis
Gene Ontology:
Molecular function: ATP binding; calmodulin binding; DNA binding; lipid binding; magnesium ion binding; protein binding; protein phosphatase 2A binding; sphingosine kinase activity; sphingosine-1-phosphate receptor activity; acetyltransferase activity; lipid kinase activity; kinase activity
Biological process: calcium-mediated signaling; cellular response to vascular endothelial growth factor stimulus; negative regulation of apoptotic process; negative regulation of ceramide biosynthetic process; positive regulation of angiogenesis; positive regulation of cell growth; positive regulation of cell migration; positive regulation of fibroblast proliferation; positive regulation of mitotic cell cycle; positive regulation of non-canonical NF-kappaB signal transduction; positive regulation of p38MAPK cascade; positive regulation of protein ubiquitination; positive regulation of smooth muscle contraction; regulation of endocytosis; regulation of tumor necrosis factor-mediated signaling pathway; response to tumor necrosis factor; sphingosine biosynthetic process; sphingosine metabolic process; cellular response to growth factor stimulus; intracellular signal transduction; positive regulation of interleukin-17 production; protein acetylation; regulation of endosomal vesicle fusion; regulation of microglial cell activation; regulation of neuroinflammatory response; and 7 more
Cellular component: clathrin-coated pit; cytoplasm; early endosome membrane; endosome membrane; nucleus; plasma membrane; presynapse; cytosol; endocytic vesicle; nucleoplasm; synapse; cytoplasmic vesicle
Genetic constraint (gnomAD): Loss-of-function variants: 11 observed, 11.73 expected, observed/expected ratio (o/e) 0.94, 90% interval 0.59 to 1.54. The upper end of that interval is the gene's LOEUF score, 1.54, which puts it in group 6 of 6, group 1 being the genes least tolerant of losing a copy. Missense variants: 553 observed, 529.35 expected, observed/expected ratio (o/e) 1.04, 90% interval 0.97 to 1.12. Synonymous variants: 274 observed, 227.72 expected, observed/expected ratio (o/e) 1.2, 90% interval 1.09 to 1.33.
Homologues: Orthologues: chimpanzee SPHK1 (99% identical), macaque SPHK1 (97% identical), dog SPHK1 (90% identical), pig SPHK1 (86% identical), rabbit SPHK1 (86% identical), mouse Sphk1 (80% identical), rat Sphk1 (78% identical), guinea pig SPHK1 (77% identical), tropical clawed frog sphk1 (51% identical), zebrafish SPHK1 (48% identical), Drosophila melanogaster Sk1 (36% identical), Drosophila melanogaster Sk2 (36% identical), and 3 more. Paralogues in human: SPHK2 (50% identical), CERK (24% identical), CERKL (22% identical), AGK (20% identical).
Diseases named in the same sentence as SPHK1 in open-access papers:
SPHK1 is named in the same sentence as 299 diseases in open-access papers, as found by Europe PMC text mining. Sharing a sentence is not in itself a finding about the gene and the disease. The quoted sentences say what the papers report.
breast carcinoma (108 papers, 2009 to 2026). "Despite the landmark success of PARP inhibitors in breast cancer therapy, the molecular mechanisms underlying resistance—particularly the pro-survival signaling mediated by sphingolipid-metabolic enzyme SPHK1—remain insufficiently understood." (PMID 41304867, 2025). "Upregulation of SPHK1 expression has been observed in various cancers, including gliomas, lung cancer, colon cancer, and breast cancer, and is associated with poor survival outcomes in glioma, lung cancer, and breast cancer 15-16." (PMID 39629135, 2024). "S1PR4 and high expression of SphK1 are associated with shorter survival in breast cancer patients, indicating the importance of S1PR4 and SphK1 in the progression of breast cancer." (PMID 38542328, 2024). "High SphK1 expression by microarray analysis was associated with significantly worse disease-free survival in combined datasets of 968 breast cancer patients." (PMID 38542328, 2024). "For example, in estrogen-responsive breast cancer cells, elevated SphK1 is associated with endocrine resistance, and the spatial organization of SphK1 in ER positive breast tumors is aligned with the prognostic outcome." (PMID 36532885, 2022). "Overexpression of SphK1 has been shown to be a mediator of estrogen signaling and is causally associated with endocrine resistance in ER+ breast cancer cells, and silencing of SphK1 activity can restore sensitivity." (PMID 36532885, 2022). "In the context of breast cancer, it has been shown that high tumor expression of SPHK1 is associated with poorer disease outcomes in breast cancer patients across different subtypes." (PMID 34820423, 2021). "Other factors have been discovered to cause an upregulation of SphK1, leading to breast cancer progression." (PMID 33758708, 2021). "In breast cancer, high SPHK1 expression was also associated with human epidermal growth factor receptor 2 (HER2) status but not with tumor histological subtypes, histological grade, tumor size or hormone receptor status." (PMID 33660008, 2021). "Nuclear localization of SphK1 has been observed in breast cancer cells, and greater nuclear SphK1 levels have been linked to advanced cancer prognosis, significantly shorter disease-specific survival, and faster cancer recurrence." (PMID 33919234, 2021). "In the current study, we demonstrated for the first time in human breast cancer that elevated inflammation was significantly associated with high expression of S1P-signaling genes, such as SphK1 and S1PR1." (PMID 33457427, 2020). "In agreement with our mechanistic model, we showed that human breast cancers with a high amount of angiogenesis are significantly associated with high expression of S1P-signaling genes, SphK1, S1PR1, and SPNS2." (PMID 32933189, 2020). "High expression of SphK1 and increased S1P levels were associated with lymphatic metastasis in breast cancer tissue." (PMID 29385066, 2018). "Estrogen stimulates SphK1 to promote breast cancer development and is also associated with breast cancer treatment resistance." (PMID 28415564, 2017). "Clinically, S1P levels have been shown to be high in patients with breast cancer, and phosphorylated SphK1 levels are associated with high S1P levels in breast tumors." (PMID 29147072, 2017). "S1P binding to S1PR3 is associated with SphK1 translocation of SphK1 to the plasma membrane to promote tumorigenesis in ER+ breast cancer." (PMID 28415564, 2017). "Similarity of the oncogenic lipid kinase (SPHK1) to leptin has led many studies done on the relationship between this gene, obesity, and breast cancer; although these mechanisms and pathways were linked with poor prognosis." (PMID 29531546, 2017). "In breast cancer cells, SphK1 activity has been linked to endocrine resistance, whereby overexpression of SphK1 resulted in resistance to tamoxifen with increased proliferation." (PMID 29147072, 2017).
breast carcinoma (continued). "SPHK1 is overexpressed in multiple types of cancer including breast cancer and is associated with resistance to treatment." (PMID 29531546, 2017). "Increased expressions of SPHKs have been observed in breast tumors and microarray analysis suggests that breast cancer patients with high levels of the SPHK1 isoform are predisposed to poorer outcomes." (PMID 25153718, 2014). "Taken together, these observations suggest that high levels of SPHK1 expression are associated with poorer prognosis and lower survival in breast cancer." (PMID 25153718, 2014). "Indeed, previous studies have reported that S1P and SphK1 are associated with outcomes in breast cancer patients." (PMID 38542328, 2024). "SPHK1 was connected to breast cancer-associated immune responses as well." (PMID 35163211, 2022). "In addition, increased SPHK1 expression is associated with a poor survival outcomes in glioma, lung cancer, and breast cancer." (PMID 36050478, 2022). "The upregulation of SphK1 has been thoroughly linked with poor prognosis in breast cancer." (PMID 33758708, 2021). "In addition to ERK, SPHK1/S1P/S1PR3 axis has been implicated in potentiating the progression of breast cancer through upregulations of C-reactive protein (CRP) and MMP9." (PMID 34820423, 2021). "Indeed, high expression of SPHK1 in tumors is associated with worse prognosis and overall outcomes in breast cancer patients." (PMID 32260399, 2020). "High SPHK1 expression associated with lymphatic metastasis is also found in human breast cancer." (PMID 31101115, 2019). "SPHK1 over-expression in breast cancer tissues is associated with a poor prognosis in humans." (PMID 31101115, 2019). "As both ERK1/2 and SPHK1 have been implicated in several oncogenic pathways, the inhibition of SPHK1 by SKI-5C may effectively down-regulate multiple molecular pathways in breast cancer by its potential to interrupt this positive feedback loop." (PMID 25153718, 2014). "On the one hand, SphK1 expression is up-regulated at the message or protein level in various solid tumors, and has been linked with poor survival for brain and breast cancers." (PMID 19956567, 2009). "Our understanding of the association between SphK1 expression in normal and malignant breast cells and this added knowledge that SphK-1a and -1b are expressed in estrogen-responsive normal and breast cancer tissue provides another avenue to explore anti-SphK novel targeted therapeutic intervention." (PMID 36532885, 2022). "A previous study conducted microarray analysis on 1269 breast cancer samples across different subtypes and found increased SPHK1 expression in cancerous tissues." (PMID 41304867, 2025). "Ampelopsin A was reported as a sphingosine kinase 1-targeted inducer of apoptosis in MDA-MB-231 breast cancer cells and possessed antifungal activity." (PMID 40141054, 2025). "Breast cancer MCF-7 cells exhibit SphK1-dependent elevation of intracellular S1P that promotes pro-survival autophagy." (PMID 40906080, 2025). "Estrogens, through the activation of sphingosine kinase 1 (SphK1), have also been observed to increase the intracellular concentration of S1P, proliferation and cell survival, at least in breast cancer." (PMID 39996745, 2025). "Analysis of publicly available breast-cancer datasets revealed that SPHK1 expression is markedly elevated in TNBC patient samples and that high SPHK1 levels are significantly associated with poor prognosis." (PMID 41304867, 2025). "Numerous studies have reported high expression levels for SPHK1 and SP1 in breast cancer tissues, which are closely associated with poor prognosis and lower survival rates." (PMID 40002245, 2025). "A breast cancer study also found a significant correlation between phosphorylated‐SPHK1 and lymph node metastases." (PMID 40356021, 2025). "SPHK1 is highly expressed in various cancers, including breast cancer, lung cancer, head and neck cancer, and gastric cancer." (PMID 41304867, 2025).
breast carcinoma (continued). "Consistently, patients with ER+ breast cancer who posse high expression levels of SPHK1 exhibit lower survival rates and increased chemoresistance." (PMID 38419070, 2024). "SphK1 enzyme is up-regulated in breast cancer with subsequent elevation of S1P and oncogenic phenotype with Ras-dependent transformation of tumor cells." (PMID 38419070, 2024). "We previously confirmed that patients with positive-expression of phosphorylated SphK1 (pSphK1) on breast cancer specimens do indeed show significantly higher levels of S1P in the breast cancer tissue as determined using mass spectrometry." (PMID 38542328, 2024). "The SphK1/S1P/S1PR axis in breast cancer cells promotes their growth, survival, dissemination and metastasis." (PMID 39767749, 2024). "The unphosphorylated FTY720 also impedes and promotes the proteasomal degradation of SphK1, which is elevated in breast cancer, correlating with unfavorable prognosis and drug resistance." (PMID 39126272, 2024). "The SphK1-S1P-S1PR1 axis has emerged to be one of the major targets in developing anticancer agents against breast cancer, and quite a few SphK1 inhibitors such as SK1-I and S1PR1 antagonists such as NIBR0213 have been developed." (PMID 37220155, 2023). "It has been shown that elevated levels of intracellular S1P through overexpression of SPHK1 induces autophagy via the inhibition of mTOR in human MCF-7 breast cancer cells." (PMID 37190124, 2023). "It was reported that SphK1 was overexpressed in many tumors, for example, prostate and breast cancers." (PMID 36909198, 2023). "Similar to the CERK, the levels of SPHK1 were found to be significantly high in patients with nodal metastasis and advanced stage of breast cancer." (PMID 36309544, 2022). "To establish the role of sphingolipids in breast cancer metastasis, we analyzed the associations of MMP-2 and MMP-9 with SPHK1 and CERK expression." (PMID 36309544, 2022). "SPHK I-II simultaneously inhibits SPHK1 and SPHK2, as well as other targets, and SPHK inhibition with SPHK I-II decreases MDR breast cancer proliferation and viability." (PMID 35965565, 2022). "A study investigating human breast cancer found elevated S1P levels in tumors compared to peritumoral or normal human breast samples to correlate with elevated SPHK1 gene expression." (PMID 35163211, 2022). "A recent study has also shown that increased export of S1P via ABCC1 enhances the transcription of SPHK1 resulting in more S1P formation in human MCF-7 breast cancer cells." (PMID 36309544, 2022). "Estrogen has been shown to induce SphK1 in both hormone-responsive breast cell lines, clinical patient breast cancer samples, and triple-negative cell lines and confer tamoxifen resistance." (PMID 36532885, 2022). "For example, a previous work performed microarray analysis on various subtypes in 1269 breast cancer samples and found increased SPHK1 expression in the tissues of patients with cancer." (PMID 35965565, 2022). "Previously, we identified the high levels of sphingolipids, ceramide phosphates and sphingosine phosphates, and the genes involved in their synthesis, CERK and SPHK1, in breast cancer patients." (PMID 36309544, 2022). "In breast cancer cells, specific protein interactions with either SphK1b or SphK1a isoform alter SphK1 signaling events." (PMID 36532885, 2022). "Upregulation of SPHK1 expression has been observed in many cancers, including glioma, lung, colon, and breast cancers." (PMID 36050478, 2022). "In the present study, we measured the expression of MMP-2 and MMP-9 in breast cancer patients and determined their correlations with SPHK1 and CERK in local as well as TCGA cohort." (PMID 36309544, 2022). "As the key kinase of S1P combination, SPHK1 has been found to be overexpressed in TNBC compared with other breast cancer subtypes, and promotes tumor metastasis." (PMID 34283088, 2021). "Other genes upregulated by the SphK1/S1P axis in breast cancer have been identified, including CERS1, CERS2, CERS6, and UGCG." (PMID 33758708, 2021).